ABCG2 (ATP binding cassette subfamily G member 2 (JR blood group))
Diseases named in the same sentence as ABCG2 in open-access papers (continued):
Sharing a sentence is not in itself a finding about the gene and the disease.
breast cancer (continued). "Deep deletions were significantly more prevalent in prostate cancer tissues compared to breast cancer tissues, where they were relatively rare and limited to ABCG2, ABCC4, ABCA2, ABCC2, and ABCC9." (PMID 40641097, 2025). "In contrast, breast cancer exhibited relatively lower deep deletion rates, restricted to ABCG2, ABCC4, ABCA2, ABCC2, and ABCC9." (PMID 40641097, 2025). "Specifically, overexpression of ABCG2 in several cancer cell lines, such as breast cancer, colon carcinoma, and stomach cancer, contributes to resistance to various anticancer drugs." (PMID 39931465, 2025). "Pan-cancer analysis revealed a negative correlation between the expression of STAT3, VEGFA, ESR2, and ABCG2 and breast cancer patient survival." (PMID 41121538, 2025). "In a subsequent study, it was identified as a substrate of the breast cancer resistance protein (BCRP/ABCG2), an essential efflux transporter associated with drug resistance in breast cancer." (PMID 40568370, 2025). "The significance of targeting ABCG2 (also known as breast cancer resistance protein/BCRP) in breast cancer and prostate cancer also been reported." (PMID 40641097, 2025). "P-glycoprotein (P-gp), multi-drug-resistant associate protein (MRP), and adenosine triphosphate-binding cassette superfamily G member 2 (ABCG2) are the most common efflux transporters in ovarian and breast cancers." (PMID 40352931, 2025). "Breast cancer cells predominantly overexpress other types of pumps such as the breast cancer-related protein ABCG2." (PMID 38969867, 2024). "Some recent studies demonstrated the regulation of ABCG2 by several other miRNAs, including miR-302a/b/c/d in mitoxantrone-resistant breast cancer cells and miR-212 in imatinib-resistant leukemia cells." (PMID 39114355, 2024). "Silencing these miRNAs reversed these molecular alterations and reduced ABCG2 expression, hence refining the sensitivity of resistant breast cancer cells to doxorubicin." (PMID 39679367, 2024). "The breast cancer resistance protein (BCRP/ABCG2) was first identified in multidrug-resistant breast cancer cells." (PMID 38324023, 2024). "In vitro dual inhibition of ABCC1 and ABCG2-mediated daunorubicin and mitoxantrone efflux was demonstrated by talazoparib, a TK inhibitor used in metastatic BCRA1/2-mutated breast cancer." (PMID 38255216, 2024). "The efficacy of the targeted inhibition of ABCG2-mediated transport has been investigated in various cancers such as colon cancer, breast cancer, and leukemia." (PMID 39457707, 2024). "The hypomethylation of ABCG2 was also confirmed in most cases of gallbladder cancer or breast cancer." (PMID 39457707, 2024). "MX-10032 is a derivative of MCF7 cells selected for stable mitoxantrone resistance that overexpresses ABCG2 (aka breast cancer resistance pump, BCRP) by 30-fold." (PMID 39217266, 2024). "Several microRNAs have been identified as key regulators of the response of breast cancer cells to doxorubicin by influencing ABCG2 expression." (PMID 39679367, 2024). "Ongoing ABCG2 research continues to reveal its significant physiological and pharmacological roles in breast cancer drug resistance and treatment." (PMID 40125243, 2024). "ABCB1, the first identified ABC transporter, is well-known for its role in drug resistance, and subsequent discoveries revealed ABCC1 and ABCG2 as contributors to multidrug resistance in lung and breast cancer cells, respectively." (PMID 38397468, 2024). "In one study, mitoxantrone-resistant breast cancer cells were able to secrete ATP binding cassette subfamily G member 2 (junior blood group) (ABCG2) proteins to exosomes to affect the neighboring breast cancer cells, inducing multidrug resistance." (PMID 36834471, 2023). "Data obtained from the TCGA database also showed a statistically significant lowered average expression level of the ABCB1, ABCC4, ABCC6, and ABCG2 genes in patients with breast cancer compared to the control group." (PMID 36674773, 2023).
breast cancer (continued). "While TGF-β1 treatment of the MCF7 breast cancer cell line eliminated the SP population, decreased ABCG2 expression and reduced cell viability in the presence of mitoxantrone." (PMID 36831452, 2023). "In vitro inhibition of ABCG2- and ABCC1-mediated daunorubicin and mitoxantrone efflux was demonstrated also by talazoparib, a drug approved for metastatic BCRA1/2 mutated breast cancer." (PMID 37108308, 2023). "In the present study, we aimed to investigate the role of miR‐548 k on ABCG2 gene expression in breast cancer cells." (PMID 37166017, 2023). "Downregulation of Cav-1 can decrease the activity of ATP-binding box family G protein subfamily 2 (ABCG2) in BCRP and improve the chemotherapy sensitivity of drug-resistant breast cancer cells." (PMID 37828916, 2023). "Several cytotoxic drugs, including those used to treat breast cancer, are substrates for ABCG2, and resistance to these drugs is thought to be the result of drug efflux by ABCG2." (PMID 37190293, 2023). "In silico inspections introduce 14 microRNAs targeting 3′‐UTR region of ABCG2 transcripts, which are probably involved in breast cancer drug resistance." (PMID 37166017, 2023). "To avoid confusion, we will be using henceforth BCRP2 as the human ABCG2, which was first isolated from multidrug resistant human breast cancer cells where it mediates resistance to the widely used drugs in breast cancer treatment anthracyclines." (PMID 36554670, 2022). "Subsequent studies confirmed a GH-regulated ABCG2 dependent docetaxel resistance in human breast cancer xenografts in Nude mice." (PMID 35865483, 2022). "Subsequent studies in Nude mice reported that GH-directed ABCG2 expression promoted docetaxel resistance in breast cancer." (PMID 35865483, 2022). "Further investigations with large cohorts will be needed to illustrate the clinical utility of ABCG2 in breast cancer patient population." (PMID 36309544, 2022). "Pharmacological inhibition frequently targets both P-gp and ABCG2 (BCRP) at once, sensitizing breast cancer to doxorubicin, and endothelial ovarian cancer cells to paclitaxel and cisplatin." (PMID 36325145, 2022). "Compared to non-stem cells, CD44+CD24−/low cells from MCF-7, MDA-MB-231, and SK-BR-3 breast cancer cell lines showed higher expression of ABCG2." (PMID 35563449, 2022). "In our qRT-PCR experiments, talazoparib did not cause significant transcriptional changes in ABCB1, ABCC1, and ABCG2 genes in the MCF-7 breast cancer cells." (PMID 36430819, 2022). "This is in line with a study of MCF7 breast cancer SP cells which also showed a reduction in ABCG2 expression and a reduction in SP numbers following TGF-β treatment, both of which were reversable on removal of exogenous TGF-β1." (PMID 35118633, 2022). "Recent studies on breast cancer stem cells have shown that ultrasound has the effect of reversing chemoresistance by altering the expression of ABCG2." (PMID 35055109, 2022). "Consistently, in breast cancer, the ABCG2 rs2231142 AA group also had a better therapeutic response in patients receiving anthracycline chemotherapy." (PMID 35566676, 2022). "The presence of ABCG2 was first demonstrated in a study of doxorubicin-resistant breast cancer cells, which gave it its second name, breast cancer resistance protein (BCRP)." (PMID 35055109, 2022). "Kurdish breast cancer patients with ABCG2 rs2231142 AA exhibited a better response to anthracycline and paclitaxel treatment." (PMID 35566676, 2022). "ABCG2, named Breast cancer resistance protein, is the main drug efflux transporter that leads to resistance in breast cancer." (PMID 35897925, 2022). "In contrast, long (12-days) exposure to talazoparib has been found to upregulate ABCB1, ABCC1, and ABCG2 mRNAs in another breast cancer model, MCF-10A." (PMID 36430819, 2022).
breast cancer (continued). "High ABCG2 expression was found in A significant number of breast cancer patients and was correlated with tumor grade, clinical stage, and lymph node metastasis, indicating its association with MDR and possible role as independent prognostic marker." (PMID 36430819, 2022). "ABCG2 is identified as an ABC transporter, a breast cancer resistance protein, that mediates S1P efflux from cells." (PMID 35565311, 2022). "Overexpression of BCRP/ABCG2 is also reported in CSCs of breast cancer, pancreatic, hematopoietic, ovarian and others." (PMID 36365249, 2022). "ABCG2 was originally discovered in human placenta, drug-resistant breast cancer cells, and drug-resistant colon cancer cells." (PMID 34830383, 2021). "It was found that multiple flavonoid combinations induce strong ABCG2 inhibition by increasing both accumulation and cytotoxicity of mitoxanthrone in ABCG2-overexpressing breast cancer cells." (PMID 34884848, 2021). "In breast cancer, hyperthermia increased intracellular ROS production and downregulated ATP-binding cassette sub-family G member 2 (ABCG2) expression—an exporter of DOX—leading to cell damage enhancement via DOX." (PMID 35008457, 2021). "ABCG2 was originally discovered in the breast cancer cell line MCF-7/Adr-vp3000, which functions as a transporter to pump chemotherapy drugs out of tumor cells." (PMID 34144706, 2021). "The ISL suppresses β-catenin signaling and decreases ABCG2 expression to enhance drug sensitivity of breast cancer cells and suppress CSC features." (PMID 34769099, 2021). "BCRP (known as ABCG2) was identified first in breast cancer cells but is mainly expressed in liver, intestine, and brain cells." (PMID 34830916, 2021). "Active Rab5a-Q79L in breast cancer cells reduced the expression of ABCG2 in the plasma membrane, decreasing ABCG2-mediated drug efflux." (PMID 34141705, 2021). "In sum, these results demonstrate that ADQ suppresses breast cancer growth by inhibiting autophagy via the GRP78/β-catenin/ABCG2 axis, thereby increasing the chemosensitivity of breast CSCs to taxol." (PMID 34149413, 2021). "On the mRNA level, the efflux transporters ABCB1, ABCC1, and ABCG2 were found expressed in human heart, in normal and tumorous breast tissue, and in human breast cancer cell lines MCF-7, MDA-MB-231, and ZR-75-1." (PMID 35008681, 2021). "Apart from ABCB1 and ABCG2, some other ABC transporters are also implicated in breast cancer metastasis." (PMID 33801148, 2021). "ABCG2 was initially identified in MCF-7 breast cancer cells giving it the nomenclature, breast cancer resistance protein (BCRP) 23,24." (PMID 34326700, 2021). "ABCG2 is recognized as a primary breast cancer-efflux transporter known as breast cancer resistance protein (BCRP)." (PMID 34680470, 2021). "Most believe that estrogen can increase the expression of ABCG2 in breast cancer cells, thereby increasing drug resistance." (PMID 34144706, 2021). "Overexpression of miR-328 in MCF-7/MX100 breast cancer cells decreased the level of ABCG2 mRNA and protein and, more importantly, increased sensitivity to mitoxantrone." (PMID 33806009, 2021). "Among various ABC transporters, the main ABC transporters primarily linked to MDR in breast cancer are P-glycoprotein (P-gp/MDR1/ABCB1), multidrug resistance-associated protein 1 (MRP1/ABCC1), and breast cancer resistance protein (BCRP/ABCG2)." (PMID 34959321, 2021). "Multiple studies have revealed that estradiol-mediated breast cancer resistance is related to alterations in ABCG2 expression." (PMID 34144706, 2021). "We examined a handful of CSC markers commonly associated with breast cancer (ALDH1A1, ABCG2, PGP, FUT4)." (PMID 34579762, 2021).
breast cancer (continued). "Flavonoids such as Chrysin and biochanin A reported as potent inhibitors of ABCG2 in breast cancer cells, and were consequently able to sensitize breast cancer stem cells to cancer chemotherapy activity such as mitoxantrone." (PMID 34884848, 2021). "The other major drug efflux pump involved in multiple drug resistance in breast cancer is the human breast cancer resistance protein (BCRP/ABCG2)." (PMID 33255471, 2020). "Recently a GH induced chemoresistance by upregulation of ABCG2 has been recently validated in breast cancer as well." (PMID 33291663, 2020). "The overexpression of ABCG2 has been found to be related to acquired MDR in multiple types of cancers including breast cancer, non-small cell lung cancer and acute myelogenous leukemia." (PMID 33364237, 2020). "When cancer cells overexpress miR-328-3p, it can obviously limit the expression of ABCG2 and decrease the drug resistance of breast cancer cells." (PMID 32792861, 2020). "The overexpression of ABCG2 has been found to confer MDR in multiple types of cancers including breast cancer, non-small cell lung cancer and acute myelogenous leukemia." (PMID 33364237, 2020). "CXCR4 increases the growth and sphere formation efficiency of hypoxic breast cancer side population (SP) cells by c-Jun/ABCG2 pathway." (PMID 32232002, 2020). "ENPP1 promotes the expression and cell surface localization of ABCG2 which is involved in the development of multidrug resistance, for example, in breast cancer, esophageal cancer, lung cancer." (PMID 32512882, 2020). "The ABCG2 transporter belongs to the family of ABC translocators (ATP-binding cassette G2 transporter) and it is also called BCRP (breast cancer resistance protein), since it was first isolated from a multidrug-resistant breast cancer cell line." (PMID 32722651, 2020). "Firstly, we found that the expression of ID4 was associated with chemo-resistant ABC transporter proteins, including MRP1, ABCG2, P-gp in breast cancer resection samples." (PMID 32328189, 2020). "Promoter methylation of ABCB1, ABCC1, and ABCG2 has been investigated in tumor, tumor-adjacent, and tumor-distant tissues from 16 breast cancer patients and normal breast tissues from four healthy women." (PMID 33066132, 2020). "In recent studies, researchers have revealed that overexpression of EMT-related transcription factors (TFs), such as snail, enhanced the chemoresistance through the induction of P-gp and ABCG2 in breast cancer cells." (PMID 31991851, 2020). "Human ABCG2 was discovered in an adriamycin/doxorubicin‐selected breast cancer cell line, MCF‐7/AdVp3000 (MCF‐7/AdrVp), and originally named Breast Cancer Resistance Protein more than 22 years ago." (PMID 32978801, 2020). "Topotecan selected drug resistance was found related to expression and efflux activity of ABCG2 expression in human breast cancer cells or overexpression of both ABCG2 and ABCB1 transporters in human ovarian cancer cells." (PMID 33425914, 2020). "Recently, PPAR δ ligands (rosiglitazone and pioglitazone) were found to inhibit drug resistance in breast cancer cells by internalization of ABCG2 to cytoplasm." (PMID 31936346, 2020). "Blockade of GHR using neutralizing antibody or pharmacological inhibition of JAK2/STAT5 inhibits ABCG2 promoter activity suggesting that GHR regulates ABCG2 through JAK2/STAT5 signaling mechanism in ER−ve breast cancers." (PMID 30617282, 2019). "This is the first study to demonstrate that GHR promotes the chemoresistance of ER−ve breast cancers by regulating ABCG2 levels." (PMID 30617282, 2019). "Immunohistochemical staining data indicated that primary breast cancers expressing high levels of GHR also stained strongly for pAKT, pmTOR, and ABCG2, demonstrating the association of GHR with these proteins in primary breast cancers." (PMID 30617282, 2019). "Other authors have also shown that ABCG2 is regulated by miR-328, miR-519c and miR-487a in breast cancer and influences MX resistance." (PMID 35582590, 2019).
breast cancer (continued). "To establish the role of ABCG2 in breast cancer chemoresistance, we overexpressed ABCG2 and treated the cells with DT." (PMID 30617282, 2019). "Further, we and others have shown a direct effect of GH–GHR action in upregulating expression of ATP-cassette-containing (ABC) multidrug efflux pumps such as ABCB1, ABCC1, ABCC2, and ABCG2 in melanoma as well as in breast cancer." (PMID 31547367, 2019). "It has been demonstrated that prolactin induces ABCG2 expression in T-47D human breast cancer cells by JAK2/STAT5." (PMID 31590349, 2019). "The data clearly suggested that GHR or ABCG2 knockdown sensitized the primary human breast cancer cells to DT." (PMID 30617282, 2019). "First to investigate the effect of GHR silencing or ABCG2 silencing on cancer progression, we used wild type or GHR knockdown or ABCG2 knockdown primary human breast cancer cells." (PMID 30617282, 2019). "Another study evaluated effects of curcumin on the reduction of breast CSCs population for sensitizing cancer cells to mitomycin C. Curcumin sensitized breast cancer cells to chemotherapy via decrease in ABC transporter (ABCG2) expression." (PMID 30836718, 2019). "Studies have confirmed that ABCG2 is closely related to the drug resistance of breast cancer and nonsmall cell lung cancer." (PMID 31949471, 2019). "The overexpression of ABCG2 in these subpopulations of stem cells was also reported among other tumors such as neuroblastomas, Ewing sarcomas, breast cancer, small cell lung cancer, and glioblastomas." (PMID 30687102, 2018). "Multidrug resistance in acute myeloid leukemia (AML), non-small cell lung cancer (NSCLC), colon carcinoma and breast cancer were also reported to be strongly correlated with the overexpression of ABCG2." (PMID 30687102, 2018). "ABCB1, ABCB5, ABCB8, ABCC1, ABCC2, ABCC3, and ABCG2 were considered to confer resistance to doxorubicin on the breast cancer cells." (PMID 30202239, 2018). "The expression of ABC transporter proteins in breast cancer cells is highly heterogeneous; thus, we selected the ABCB superfamily, the ABCC superfamily, and ABCG2, which are strongly associated with drug resistance in breast cancer cells." (PMID 30202239, 2018). "The nimbolide activity was also tested in breast cancer cells transduced with cDNA for ABCG2/BCRP and compared with sensitive cells transduced with a control vector." (PMID 30515268, 2018). "The ABC transporter ABCG2, also known as breast cancer resistance protein (BCRP) or mitoxantrone resistance-associated protein (MXR), was cloned independently in 1998 from both a drug-selected human breast cancer cell line and a human cDNA library." (PMID 29867471, 2018). "ISL has also been reported to target GRP78 to chemosensitize breast cancer stem cells via β-catenin/ABCG2 signaling." (PMID 30174606, 2018). "Although increased NRP-1 expression in wild-type BT-474 4xAC cells is associated with lower expression of ABCG2, these cells display a more resistant phenotype, thus indicating that NRP-1 is a more predictive marker of chemoresistant breast cancer than ABCG2." (PMID 29728077, 2018). "The roles of ATP-binding cassette transporters, such as ABCC1, ABCC11, and ABCG2, in breast cancer patients have been reported." (PMID 28912626, 2017). "ABCB1 3435TT and ABCG2 421CC genotypes were significantly correlated with longer PFS of the breast cancer patients." (PMID 29340035, 2017). "Combined treatment of GS with bexarotene a retinoid X receptor agonist resulted in cytotoxicity via downregulation of BCRP/ABCG2 in breast cancer cell line." (PMID 28261317, 2017). "This study analyzed the correlation between the clinicopathological features of breast cancer patients and ABCB1 C3435T and ABCG2 C421A gene polymorphisms." (PMID 29340035, 2017). "ATP-binding cassette sub-family G member 2 (ABCG2) was first named as Breast Cancer Resistance Protein in the 1990s when it was discovered in MCF-7 breast cancer cell line co-selected for doxorubicin in the presence of verapamil." (PMID 28347288, 2017).